ATP1A1 (ATPase Na+/K+ transporting subunit alpha 1)
Diseases named in the same sentence as ATP1A1 in open-access papers (continued):
Sharing a sentence is not in itself a finding about the gene and the disease.
tumor (39 papers, 2015 to 2026). "Specifically, we observed 31 genes that were highly expressed and hypomethylated, including genes associated with tumor cell proliferation and migration, such as ATP1A1, EPCAM, TOP2A, and KIF2C." (PMID 38730618, 2024). "As the association between the transcriptional activation of a major tumor suppressor gene, FoxO3, and ATP1A1 signaling has been established, we proceed to explore the association of the ATP1A1 and the pro-autophagic gene, FoxO1 in MASH-HCC." (PMID 37830582, 2023). "More importantly, our research demonstrates the loss or downregulation of ATP1A1 relates with higher RCC tumor grades and patient’s poor prognosis." (PMID 28484360, 2017). "Similarly, analysis of the correlation between ATP1A1 expression and tumor mutational burden (TMB) revealed a positive association in SKCM." (PMID 40821775, 2025). "These membrane protein(s) may likely mask tumor cells’ ouabain binding site or alter ATP1A1’s conformation, resulting in the loss of these activities in tumor cells." (PMID 35618735, 2022). "However, the decreased expression level of ATP1A1 in RCC is negatively associated with the tumor malignant degrees (TNM stage) with statistical significance." (PMID 28484360, 2017). "To investigate the clinical association of LAPTM4B and ATP1A1 with acquired EGFR-TKI resistance, we further analyzed paired tumor biopsies from six patients with EGFR-mutant NSCLC collected before treatment and after acquisition of EGFR-TKI resistance." (PMID 41362742, 2026). "Immunohistochemical analysis revealed marked upregulation of both LAPTM4B and ATP1A1 in post-resistance tumor samples compared to matched pre-treatment samples from the same patients." (PMID 41362742, 2026). "LncDARS‐AS1 was stably knocked down, followed by ATP1A1 overexpression, enabling the assessment of the functional interaction between these molecules in regulating tumor growth and metastasis." (PMID 40665639, 2025). "Mechanistically, ATP1A1 triggers an immunosuppressive tumor microenvironment through multidimensional crosstalk with the ammonia metabolism-immune checkpoint axis." (PMID 40821775, 2025). "It has been shown that disruption of ion gradients in tumor cells caused by ATP1A1, can synergize with MAPK pathway inhibitors to promote tumor regression." (PMID 40831924, 2025). "Protein expression analysis revealed significant differences in ATP1A1 levels between tumor and normal tissues." (PMID 40821775, 2025). "Analysis of the tumor immune microenvironment revealed that ATP1A1 expression was significantly correlated with endothelial cells and naïve B cells." (PMID 40821775, 2025). "Specifically, ATP1A1 protein expression was significantly reduced in the tumor samples of KIRC, GBM, LUAD, and PAAD compared to normal tissues." (PMID 40821775, 2025). "Functional assays confirmed that ATP1A1 knockdown significantly promoted tumor cell proliferation, migration, and invasion." (PMID 40821775, 2025). "It was confirmed that ATP1A1 overexpression increased the tumor-sphere area, and the effect of digoxin was reduced in cells in which ATP1A1 was transfected compared to cells in which it was not overexpressed." (PMID 38730618, 2024). "By targeting ATP1A1, bufalin inhibited cell proliferation, induced apoptosis in vitro, and effectively suppressed tumor development in mice." (PMID 38178183, 2024). "The activation of the ROI amplification loop at the ATP1A1 signalosome favored tumor progression by enhancing epigenetic instability, creating a paucity of cell autophagic activity." (PMID 37830582, 2023). "In the present study, we found that ATP1A1 from tumor cells binds fibroblast ATP1A1 at the plasma membrane for adhesion and induces downstream signaling." (PMID 35618735, 2022). "Mechanistically, ATP1A1 overexpressed in tumor cells binds to and reorganizes ATP1A1 of fibroblasts that induces calcium oscillations, NF-κB activation, and activin A secretion." (PMID 35618735, 2022).
tumor (continued). "The positive signals of ATP1A1 were co-localized with RFP or GFP signals at the tumor-fibroblast interface." (PMID 35618735, 2022). "Women with ERα-negative BC display a significantly increased relapse-free survival (RFS) only when the tumor expresses low levels of ATP1A1." (PMID 36232400, 2022). "On the other hand, we observed that re-organization of fibroblast ATP1A1 with binding to tumor ATP1A1 complex induced calcium flux and activated the NF-κB pathway." (PMID 35618735, 2022). "Taken together, binding to high amounts of ATP1A1 of tumor cells enhances the amount of ATP1A1 at adhesion junctions of fibroblasts and triggers calcium oscillations, NF-κB activation, and activin A production." (PMID 35618735, 2022). "We conclude that homophilic ATP1A1 interactions between tumor cells and fibroblasts trigger activin A secretion from fibroblasts that promotes tumor progression." (PMID 35618735, 2022). "Silencing ATP1A1 expression or neutralizing activin A secretion suppress tumor invasion and colonization." (PMID 35618735, 2022). "Targeting ATP1A1 with doxorubicin-encapsulated nanoparticles with a peptide against ATP1A1 improved anti-tumor efficacy in breast cancer." (PMID 35618735, 2022). "INHBA was expressed by tumor-adjacent spindle-shaped cells and expression levels were positively correlated with those of ATP1A1 at the tumor-stromal interface." (PMID 35618735, 2022). "Our study highlights the importance of tumor-supporting niches modified by direct contact between ATP1A1-overexpressing tumor cells and fibroblasts." (PMID 35618735, 2022). "As described in this report, the mechanism that facilitates the formation of circulating tumor-fibroblast clusters through homophilic ATP1A1 interactions is of importance in PDAC." (PMID 35618735, 2022). "ATP1A1 was enriched in basolateral membranes for tumor-tumor contacts and tumor-fibroblast contacts." (PMID 35618735, 2022). "The expression of ATP1A1 in tumor tissues is higher than in surrounding tissues, and only about 30% of ATP1A1 participates in the function of NKAs." (PMID 34690763, 2021). "Second, a more targeted method of capturing CYP11B2-expressing tumor cells followed by sequencing was recently proposed, which increased the frequency of CACNA1D and ATP1A1 somatic mutations." (PMID 34572353, 2021). "Somatic mutations in KCNJ5, ATP1A1, ATP2B3, CACNA1D and CTNNB1 have been described in ~60% of these tumours." (PMID 31000732, 2019). "The results showed that sh-ATP1A1 xenografts had significantly lower tumor volumes than sh-NC xenografts." (PMID 31114755, 2019). "So far, ATP1A1 is a promising tumor biomarker to develop antitumor drug or to monitor therapy efficiency." (PMID 28484360, 2017). "The ATP1A1 shows a significantly decreased expression in human RCC tissues than in the adjacent non-tumor tissues." (PMID 28484360, 2017). "The overexpression of ATP1A1 was significantly more frequent in tumor parts than their adjacent normal parts in 126-paired samples (p < 0.0001; McNemar's test)." (PMID 27845894, 2016). "In contrast, we found only one tumor in the ATP1A1-shRNA-transfected MHCC97H group 40 days after implantation." (PMID 26334094, 2015). "Moreover, nanoparticle-mediated targeting of ATP1A1 has been shown to enhance the anti-tumor efficacy of doxorubicin in breast cancer models." (PMID 41362742, 2026). "Interestingly, the expression of LAPTM4B positively correlated with the ATP1A1 levels in these tumor samples from nude mice." (PMID 41362742, 2026). "Notably, LAPTM4B and ATP1A1 expression levels were positively correlated across tumor specimens, further supporting a cooperative role for these two proteins." (PMID 41362742, 2026). "Additionally, Ki67 immunostaining of both primary tumors and lung tissues showed a marked decrease in Ki67‐positive cells following ATP1A1 knockdown, indicating suppressed tumor cell proliferation." (PMID 40665639, 2025).
tumor (continued). "ATP1A1, the core subunit of the sodium-potassium pump, may contribute to ammonia-induced cell death and tumor immune evasion by disrupting ionic homeostasis and reprogramming ammonia metabolism." (PMID 40821775, 2025). "Thus, our findings strongly support ATP1A1 as a promising therapeutic target, with bufalin as a potential agent to disrupt its tumor-promoting activity." (PMID 38178183, 2024). "Furthermore, ATP1A1 knockdown significantly reduced the viability and tumor-sphere formation of TNBC cells." (PMID 38730618, 2024). "In conclusion, our results suggested that 5 might have the antitumor mechanism of directly inducing tumor cell apoptosis by inhibiting ATP1A1-related AKT-ERK signaling pathways and regulating the function of macrophages in co-cultivation." (PMID 36985801, 2023). "Furthermore, we proposed that the normalization of ATP1A1 signaling restored its tumor suppressor role through a cellular apoptotic switch-on mediated by a balance on the Survivin–SMAC proteins." (PMID 37830582, 2023). "ATP1A1 is a Na+/K+ pump and is important for tumor metastasis." (PMID 36949074, 2023). "Consistently, intracellular Ca2+ concentration was specifically up-regulated in fibroblasts during direct co-culturing with ATP1A1-overexpressing tumor cells, while inhibition of ATP1A1 interaction through silencing ATP1A1 in tumor cells diminished the intracellular Ca2+ concentration." (PMID 35618735, 2022). "This re-organization may strengthen homophilic ATP1A1 interaction between tumor cells and fibroblasts." (PMID 35618735, 2022). "Therefore, tumor cells and fibroblasts both express ATP1A1 at the junctions between the two cell types." (PMID 35618735, 2022). "On the contrary, women with ERα-positive BC have a significantly higher survival probability when the tumor expresses high levels of ATP1A1 or ATP1B1 while no significant changes in RFS of women with ERα-positive BC have been evidenced considering the ATP1A2 mRNA expression." (PMID 36232400, 2022). "To further confirm that ATP1A1 plays a major role in mediating tumor progression, we performed direct contact-mediated sphere formation, 3D spheroid invasion, and liver colonization assays using tumor cells with shRNA-mediated ATP1A1 knockdown (compared to control shRNA)." (PMID 35618735, 2022). "On the contrary, ATP1A1 in tumor cells loses these properties." (PMID 35618735, 2022). "Similarly, we found that ATP1A1 serves simultaneously as a signaling receptor and adhesion molecule during tumor-fibroblast contact." (PMID 35618735, 2022). "Tumor cells depleted of ATP1A1 demonstrated a reduction in all three activities." (PMID 35618735, 2022). "In this study, we first observed that PNS could reduce the expression of ATP1A1 in tumor tissues of tumor-bearing mice." (PMID 34690763, 2021). "The tumor regrowth capacity of ATP1A1-knockdown GSCs was evaluated in xenograft model mice." (PMID 31114755, 2019). "In addition, tumor weight was significantly lower in both sh-ATP1A1 groups than in the sh-NC group (GBM GSCs1: 0.62 and 0.264, respectively; GBM GSCs2: 0.08 vs. 0.024 g, respectively, P < 0.05 by Student's t-test)." (PMID 31114755, 2019). "In the fifteen tumours subjected to RNA-Sequencing in this study, opposite patterns of expression in tumours with mutations in KCNJ5 and those with mutations in CACNA1D/ATP1A1/ATP2B3 were observed, with KCNJ5-mutants showing higher levels of CYP11B1 expression and lower levels of CYP11B2 expression." (PMID 31000732, 2019). "Within these, alteration in ATP1A1 may pre-dispose to well-differentiated tumours, whereas alterations in GRHL2 may pre-dispose to more poorly differentiated and potentially poorer prognosis tumours." (PMID 30202019, 2018). "ATP1A1 of tumor cells may cooperate with other membrane proteins to bind to fibroblast’s ATP1A1." (PMID 35618735, 2022). "Moreover, knockdown of ATP1A1 impaired the proliferation and migration of tumor cells." (PMID 32684846, 2020).
tumor (continued). "Therefore, ATP1A1 expression varies in different tumor types." (PMID 28484360, 2017). "A comparative analysis revealed that five sodium ion transport-related genes—FXYD2, ANK3, ATP1A1, PRSS8, and CHP1—were significantly downregulated in malignant cells, implicating their potential involvement in tumor suppression." (PMID 40723891, 2025). "Mechanistically, LncDARS‐AS1 interacts with the ATP1A1‐UBQLN4 complex, preventing the ubiquitination and subsequent degradation of ATP1A1, thereby enhancing Na+/K+ ATPase (NKA) activity and promoting tumor growth and metastasis." (PMID 40665639, 2025). "For the spatial visualization of RNA and gene expression, we found that the prognostic genes from XGBoost model, especially GNAS, ATP1A1, ATP1B1, colocalized with the densest regions of tumor." (PMID 39678375, 2024). "Expanded analysis of the METABRIC and GEO (GSE38959) datasets indicated that ATP1A1 is upregulated in basal-like subtype and TNBC tumor samples." (PMID 38730618, 2024). "We also assessed the effect of ATP1A1 knockdown on the self-renewal potential and clonogenic survival of TNBC cells, finding that ATP1A1 siRNAs reduced the number and area of tumor spheres as well as colony formation ability." (PMID 38730618, 2024). "Among them, FLRT3, ATP1A1, and KCNJ15 were expressed at decreased levels in tumor samples, and the expression of SAA1 was increased in tumor samples." (PMID 38358909, 2024). "ATP1A1 and ATP1A3 were highly expressed in tumor tissues, whereas ATP1A2 and ATP1A4 were highly expressed in normal tissues (all p < 0.001)." (PMID 32684846, 2020). "We further examined the ATP1A1 mRNA and protein expression in 14 pairs of HCC samples obtained from the tumor bank at Eastern Hepatobilliary Surgery Hospital (Shanghai, China)." (PMID 26334094, 2015). "In conclusion, these findings suggest that ATP1A1 methylation and expression may be a useful specific prognostic marker for TNBC and that altered genome-wide methylation in TNBC may be critical for tumor progression." (PMID 38730618, 2024). "Specifically, the expression of ATP1A1 was approximately 18-fold higher in tumor samples from non-responders compared to responders." (PMID 38178183, 2024). "5-aza-dC increased ATP1A1 expression and tumor-sphere area compared to the control, indicating that ATP1A1 expression is regulated by methylation status and that high expression of ATP1A1 increases TNBC tumor spheres." (PMID 38730618, 2024). "Binding of STING with VDAC2, ATP2A2, and ATP1A1 was confirmed in both A498 and RCC10 tumor cells." (PMID 36445063, 2023). "On the other hand, APA with ATPA2B3 mutations tended to be dominated by compact ZG like cells, while APA with ATP1A1 and CACNA1D mutations showed heterogeneity from tumor to tumor with no clear advantage." (PMID 36012306, 2022). "Intriguingly, homophilic ATP1A1 interaction turns on activin A secretion from fibroblasts, but not tumor cells." (PMID 35618735, 2022). "Among the 80 RCC patients, the expression of ATP1A1 had no obvious differences for gender, age and tumor size (P > 0.05)." (PMID 28484360, 2017). "We used intracellular hydrogelation procedures to enrich plasma membrane fractions of BxPC-3 cells and PSCs and found that the amount of plasma membrane-localized ATP1A1 in fibroblasts, but not in tumor cells, was specifically increased upon direct tumor-fibroblast contact." (PMID 35618735, 2022). "Interestingly, the increased membrane-localized ATP1A1 in fibroblasts during direct contact relied on high ATP1A1 expression in tumor cells, but not in ATP1A1-knockdown tumor cells." (PMID 35618735, 2022). "RNA sequencing data showed that the primary signaling pathways activated in fibroblasts upon direct contact with ATP1A1-overexpressing tumor cells (BxPC-3 and SU.86.86 cells, but not MIA PaCa-2 and PANC-1 cells) were calcium-dependent axonal guidance and CREB signaling." (PMID 35618735, 2022).
tumor (continued). "We detected ATP1A1 in RCC with LC–MS/MS, and further validated its expression with immunohistochemical analyses of 80 pairs of the RCC tumor and non-tumor tissues samples." (PMID 28484360, 2017).
infection (10 papers, 2016 to 2025). The state of being infected such as from the introduction of a foreign agent such as serum, vaccine, antigenic substance or organism. "ATP1A1 also has been implicated as a pro-viral factor in the infection cycles of Ebola virus, coronavirus, hepatitis C virus, and mammarenaviruses, but the nature and mechanism of its involvement for those viruses remains largely unknown." (PMID 31381610, 2019). "Our findings suggest that clinically approved inhibitors of ATP1A1, like digoxin, could be repurposed to treat infections by mammarenaviruses pathogenic for humans." (PMID 29462184, 2018). "We found that WSSV infection promoted PvATP1A oligomerization and clustering at the early infection stages, a characteristic feature also observed in ATP1A1, a receptor for RSV." (PMID 39964166, 2025). "Recent studies have shown that ATP1A1 is a pro-viral factor with distinct roles in the infection cycles of various viruses." (PMID 39964166, 2025). "Pre-incubation of IPEC-J2 and Vero-E6 cells with a 16,000-fold dilution of ATP1A1 mAb was followed by infection with PEDV, and a significant reduction in the daughter virus was demonstrated by TCID50 assay and IFA data." (PMID 36835408, 2023). "At the time of infection of 1 h, the ATP1A1 and S1 co-localization phenomenon is more obvious on Vero-E6 than IPEC-J2 cells." (PMID 36835408, 2023). "ATP1A1, sodium/potassium-transporting ATPase subunit α-1, was the most promising candidate on this list as it had proven functional significance on the infection of all three enveloped viruses tested in our study." (PMID 35926873, 2022). "We also provided evidence suggesting that the ATP1A1-Src-EGFR signaling occurs predominantly in the cholesterol-rich domains of the caveolae which are thus important for efficient infection." (PMID 31381610, 2019). "The apical ATP1A1 seemed to increase in amount over time following infection, suggesting its recruitment to the apical surface." (PMID 31381610, 2019). "We observed a striking phenomenon in which ATP1A1 formed clusters in the plasma membrane within 15 minutes following infection with RSV." (PMID 31381610, 2019). "For this, we transfected A549 cells with siRNA targeting ATP1A1 or with NC siRNA 72 h prior to infection with rLCMV/ZsG." (PMID 29462184, 2018). "We observed the co-localization of PEDV S1 and ATP1A1 protein in the early stages of infection." (PMID 36835408, 2023). "In addition, ATP1A1 plays a crucial role in the infection of host cells by Ebola and respiratory syncytial virus (RSV)." (PMID 34671410, 2021). "Given the very early appearance of ATP1A1 clusters, independent of viral transcription or replication, we hypothesized that ATP1A1 might be involved in an early step of infection such as viral entry." (PMID 31381610, 2019). "The ATP1A1-specific inhibitors Ouabain (a cardiac steroid) and PST2238 (a digitalis toxin derivative), which specifically bind ATP1A1, could block the ATP1A1 protein internalization and degradation, and consequently reduce the infection rate of host cells by PEDV significantly." (PMID 36835408, 2023). "PST2238 in particular is a drug that already has been shown to be well-tolerated in humans, specifically acts on ATP1A1, decreases the efficiency of infection by reducing the RSV-ATP1A1 signaling needed for entry, and could be further developed as an antiviral drug for RSV." (PMID 31381610, 2019). "On the contrary, MOPV infection led to the late (48 h) release of PSMD2, RPS11, HNRNPA3, ATP1A1, TARS1, and PRKAR1A, whereas significantly elevated levels of IGFBP3 were found at both timepoints." (PMID 35337059, 2022). "Upon infection with RSV, ATP1A1 clusters were visible as early as 1 h p.i., which became more noticeable and larger at 5 h p.i.." (PMID 31381610, 2019). "Furthermore, we found that the host protein ATP1A1 was involved in PEDV attachment and co-localized with PEDV S1 protein in the early stage of infection." (PMID 36835408, 2023).